DPP8 (dipeptidyl peptidase 8)
Diseases named in the same sentence as DPP8 in open-access papers (continued):
Sharing a sentence is not in itself a finding about the gene and the disease.
type 2 diabetes (1 paper, 2015). "Interestingly, vildagliptin, a DPPIV inhibitor already on the market to treat type 2 diabetes, but with poorer selectivity toward DPP8 and 9, was shown to enhance parthenolide’s anti-leukemic activity through its inhibition of DPP8 and 9, and not DPPIV." (PMID 26300881, 2015).
tumor (14 papers, 2013 to 2025). "Dysregulated DPP8/9 levels and activities have been linked to tumour development, organ fibrosis, the initiation of pyroptosis, and inflammatory responses." (PMID 40355159, 2025). "In summary, DPP8/9 is involved in the occurrence and development of various tumors and play different roles in different tumor types and tumor stages." (PMID 36172198, 2022). "In multiple myeloma, inhibition of DPP8 activity and expression can exert anti-tumor effects by inducing apoptosis." (PMID 36172198, 2022). "Recent studies showing that the serine dipeptidases DPP8/9 inhibit activation of NLRP1 has put renewed interest in past studies on inhibitors of these peptidases (like talabostat) as anti‐tumor agents." (PMID 32027447, 2020). "DPP9 and its closest relative, DPP8, are primarily under study in cell biology, immunobiology and tumor biology." (PMID 24223149, 2013). "Studies have shown that DPP8/9 may participate in the proliferation, apoptosis, migration, and invasion of tumor cells." (PMID 36172198, 2022). "Moreover, DPP8/9 is also involved in the regulation of some tumor cell proliferation and apoptosis, which will be discussed in the tumor section." (PMID 36172198, 2022). "Burgeoning evidence have shown that DPP8/9 plays essential roles in various biological processes and diseases, such as tumor development, immune regulation, inflammatory response, energy metabolism, cell proliferation and apoptosis, and cell adhesion and migration." (PMID 36172198, 2022). "Moreover, an adjuvant effect triggered by inhibition of DPP9 and DPP8 appears to be a mechanism by which the compound Val-boro-Pro mediates tumor regression." (PMID 24223149, 2013). "Inhibition of DPP4, DPP8, DPP9 and FAP by Val-boroPro has been shown to mediate regression in multiple tumour models, likely, at least in part, via the modulation of immune responses." (PMID 34771657, 2021). "The potential importance of DPP9 in tumor biology has also been shown by inhibition of DPP9 and DPP8 enhancing parthenolide's anti-leukemic activity in primary acute myeloid leukemia samples and lymphoma and leukemia cell lines." (PMID 24223149, 2013). "Therefore, the effect of DPP8 and DPP9 on tumor cell proliferation and apoptosis seems to be cell-type-specific." (PMID 37626841, 2023). "The specific substrate or pathophysiological significance on cancer of DPP-8 and DPP-9 are not elucidated yet, but some tumor-promoting effects of either DPP-8 or DPP-9 have been reported." (PMID 34063285, 2021).
cancer (13 papers, 2013 to 2025). A tumor composed of atypical neoplastic, often pleomorphic cells that invade other tissues. "However, one study suggested that DPP8, a cytosolic protease linked to cancer biology and N-terminal dipeptidyl peptidases, is a potential therapeutic target for T2DM, albeit information on its 3D structure or binding mechanisms was lacking." (PMID 38034011, 2023). "Somehow, DPP8 is related to cell survival, as DPP8 inhibitors induce apoptosis in some types of cancer." (PMID 40076950, 2025). "In some cancers, increased DPP8/9 transcript levels indicated lowered patient survival, whereas in others, the situation was vice versa." (PMID 40355159, 2025). "Grassypeptolides show high cytotoxicity against a variety of human cancer cell lines due to inhibitory effects on dipeptidyl peptidase 8 (DPP8) and T‐cell activation." (PMID 34846772, 2022). "We highlight the new insights of DPP8/9 in pyroptosis, cancer, and organ fibrosis, as well as the research progress of selective DPP8/9 inhibitors." (PMID 36172198, 2022). "Dipeptidyl peptidase (DPP) 9, DPP4, DPP8 and fibroblast activation protein (FAP) are the enzymatic members of the DPP4 family of serine proteases and have been implicated in cancer pathogenesis." (PMID 33915844, 2021). "There were many more DPP8 than DPP9 LoF gene variants in TCGA, found in diverse types of cancer, mostly in UCEC and one in HCC." (PMID 33915844, 2021). "Thus, targeting DPP8/9 is considered an effective therapeutic approach to, for example, sensitize cells for cancer therapies." (PMID 40355159, 2025). "A later cancer study showed that dipeptidyl peptidase 8/9 (DPP8/9) inhibitor-induced pro-CASP1-dependent pyroptosis is mediated by CARD8, implicating it for the first time as an inflammasome sensor, though its natural ligands, function, and mechanism of activation were still unclear." (PMID 35746649, 2022). "Indeed, we and others have demonstrated that DPP8/9 inhibitors induce pyroptotic cell death in many monocyte-derived cancer cell lines and primary bone marrow-derived macrophages (BMDMs), but not in cells derived from many other lineages." (PMID 32796818, 2020). "For different cancer cells, DPP8/9 activity might be indicative of patient survival." (PMID 40355159, 2025). "It remains to be established whether compounds that, in addition to DPP-IV, inhibit other DPP-IV-like proteases, such as FAP, DPP8, and DPP9, may offer advantages over the use of more selective DPP-IV inhibitors in patients with cancer." (PMID 35565202, 2022). "DPP8 and DPP9 have been assigned important roles in different physiological settings including roles in the immune system, in inflammation, in preadipocyte differentiation, and during cancer progression." (PMID 32815200, 2020).
hematologic malignancies (2 papers, 2022 to 2023). "DPP8/9 inhibitors have the potential to treat hematological diseases, but their potential side effects, such as induction of resting lymphocytes pyroptosis, are still unclear." (PMID 36172198, 2022). "In recent years, related research on immune cell pyroptosis has made DPP8/9 a new potential target for the treatment of hematological diseases." (PMID 36172198, 2022). "DPP8/9 inhibition induces either pyroptotic or apoptotic cell death in hematological malignancies." (PMID 37048172, 2023). "Our findings suggest that additional enhancement in DPP8 selectivity by further modifications of tominostat chemical structure may lead to the development of novel anticancer agents that are effective against a wide range of hematologic malignancies." (PMID 37048172, 2023). "On the other hand, inhibitors which simultaneously inhibit both DPP8 and DPP9 have been demonstrated to be potential therapeutic agents for selected hematologic malignancies." (PMID 37048172, 2023).
blood cancer (1 paper, 2023). "High concentrations of 1G244 induced apoptotic cell death via DPP8, even in blood cancer cell lines resistant to pyroptosis induced by talabostat and low concentrations of 1G244 via DPP8/9." (PMID 37048172, 2023).
infection (1 paper, 2015). The state of being infected such as from the introduction of a foreign agent such as serum, vaccine, antigenic substance or organism. "In addition, RNAi of DPP8 in vivo caused no change in parasitaemia indicating that, even if DPP8 does have activity in the host bloodstream, this does not affect the progression of infection." (PMID 25816352, 2015).
kidney diseases (1 paper, 2022). "The evidence of altered expression of DPP8/9 in the kidneys of CKD patients has suggested that DPP8/9 may play an essential role in the development and progression of kidney diseases." (PMID 36172198, 2022).
DPP8 also shares sentences with these, for which no sentence is quoted: Reticulocytopenia (3 papers); Thrombocytopenia (3); Alzheimer disease (1); autism (1); Cerebral ischemia (1); Ewing sarcoma (1); gynecological cancer (1); inflammatory bone disorders (1); multiple myeloma (1); non-small cell lung carcinoma (1); pancreatic cancer (1); prostate carcinoma (1); sarcoma (1); testicular cancer (1); transient cerebral ischemia (1); Waldenstrom macroglobulinemia (1).